ZNF775 (zinc finger protein 775)
Description:
May be involved in transcriptional regulation.
Synonyms: MGC33584
Tractability: PROTAC: UniProt records ubiquitination sites on it.
Gene: Protein-coding gene on chromosome 7 (150,368,790 to 150,398,634, forward strand). Ensembl gene ENSG00000196456.
Subcellular location: Nucleus
Pathways (Reactome):
Gene expression (Transcription): Generic Transcription Pathway
Gene Ontology:
Molecular function: protein binding; DNA-binding transcription factor activity; DNA-binding transcription factor activity, RNA polymerase II-specific; RNA polymerase II cis-regulatory region sequence-specific DNA binding
Biological process: regulation of transcription by RNA polymerase II
Cellular component: nucleus
Genetic constraint (gnomAD): Loss-of-function variants: 2 observed, 2.08 expected, observed/expected ratio (o/e) 0.96, 90% interval 0.35 to 1.87. That is too few expected variants to judge how well the gene tolerates losing a copy. Missense variants: 823 observed, 659.52 expected, observed/expected ratio (o/e) 1.25, 90% interval 1.18 to 1.32. Synonymous variants: 381 observed, 292.53 expected, observed/expected ratio (o/e) 1.3, 90% interval 1.2 to 1.42.
Homologues: Orthologues: chimpanzee ZNF775 (97% identical), mouse Zfp719 (26% identical), mouse Zfp141 (25% identical), tropical clawed frog xlcof28 (25% identical), mouse B020011L13Rik (23% identical), macaque ZNF517 (23% identical), Drosophila melanogaster Meics (22% identical). Paralogues in human: ZNF189 (31% identical), ZNF229 (31% identical), ZNF182 (30% identical), ZNF226 (30% identical), ZNF234 (30% identical), ZNF33B (30% identical), ZNF606 (30% identical), ZNF483 (30% identical), ZNF717 (30% identical), ZNF235 (30% identical), ZNF7 (30% identical), MZF1 (30% identical), and 164 more.
Diseases named in the same sentence as ZNF775 in open-access papers:
ZNF775 is named in the same sentence as 3 diseases in open-access papers, as found by Europe PMC text mining. Sharing a sentence is not in itself a finding about the gene and the disease. The quoted sentences say what the papers report.
hepatocellular carcinoma (1 paper, 2024). A malignant tumor that arises from hepatocytes. "The Zinc Finger Protein 775 (ZNF775) has been predicted to enable the DNA-binding transcription factor activity and found to have strong predictive value for the OS in the hepatocellular carcinoma patients, however, the functional role of this protein has not been explored in detail." (PMID 38163849, 2024).
melanoma (1 paper, 2021). A malignant, usually aggressive tumor composed of atypical, neoplastic melanocytes. "The findings showed that ZNF775, GBA, ALKBH5, ZFYVE1, and MIEF2 were significantly upregulated in Treg cells of metastatic melanoma compared with primary melanoma." (PMID 34159752, 2021).
ZNF775 also shares sentences with these, for which no sentence is quoted: metastatic melanoma (1 paper).